PTH (parathyroid hormone)
Diseases named in the same sentence as PTH in open-access papers (continued):
Sharing a sentence is not in itself a finding about the gene and the disease.
hyperparathyroidism (continued). "Although two patients were affected by severe uncontrolled hyperparathyroidism [PTH values between 1527 and 2450 pg/mL], the role of hyperparathyroidism on the pathogenesis of OF in the setting of end-stage renal disease remains unclear." (PMID 27800197, 2016). "Thus, despite the PTH is in the normal range (usually 10–65 pg/ml), it is indicative of hyperparathyroidism." (PMID 27335606, 2016). "However, in the case of hyperparathyroidism, PTH level become elevated which triggers the excess release of calcium into the bloodstream." (PMID 26932583, 2016). "Knowledge of the effects of continuous exposure to PTH is, however, limited with regard to the regulation of mineralisation-promoting enzymes despite an overall increase in the remodelling rate observed in hyperparathyroidism." (PMID 27444010, 2016). "However, it cannot be completely ruled out that the direct damage to the kidneys by PA partly induced secondary (renal) hyperparathyroidism, or that aldosterone and PTH interacted with each other, because the PTH level was decreased after ADX." (PMID 24343173, 2015). "On the other hand, PTH could be decreased with other pharmacological treatments such as aldosterone antagonists, known to prevent hyperparathyroidism and its consequences." (PMID 26308451, 2015). "These associations suggest plausible mechanisms whereby the elevated PTH concentrations that result from hyperparathyroidism may be involved in various pathological processes that lead to circulatory disease." (PMID 33530149, 2015). "PTH levels at 4 weeks post-transplantation might serve as a marker for the occurrence of hypercalcaemic hyperparathyroidism during follow-up." (PMID 25606342, 2014). "The mechanisms through which excess PTH blunts insulin sensitivity are still uncertain, but medical treatment of hyperparathyroidism in patients with CKD could lead to correction of glucose intolerance." (PMID 24839054, 2014). "Adjusted odds ratios (ORs) with 95% confidence intervals (95% CIs) for hyperparathyroidism (defined as parathyroid hormone>70 pg/mL) by creatinine-corrected urinary concentrations of perchlorate, nitrate, and thiocyanate among the United States adults, NHANES 2005–2006." (PMID 25514572, 2014). "Indeed, we observed an increase in the PTH serum concentration in 2 cases, which rose presumed hyperparathyroidism in the BP + PPI group." (PMID 25436170, 2014). "Hyperparathyroidism is defined by an increased activity of the parathyroid glands, either from an intrinsic abnormal change altering PTH excretion (primary or tertiary) or from an extrinsic change stimulating PTH production (secondary)." (PMID 25514572, 2014). "Hyperparathyroidism has been observed in a large proportion (25-48%) of morbidly obese subjects, and in the present study 18% of the patients had PTH above normal range." (PMID 23961416, 2013). "The patient was then assured that the high PTH level was due to the site of phlebotomy and that she did not have hyperparathyroidism and that her memory loss and her dysphagic spell were not due to the manifestations of recurrent hyperparathyroidism." (PMID 23710381, 2013). "When compared to those that did not need PTX, we could observe that these patients with refractory hyperparathyroidism presented higher serum phosphorus, alkaline phosphatase and serum PTH." (PMID 23940515, 2013). "The median PTH in all patients with hyperparathyroidism was 90 pg/ml (range: 66–200)." (PMID 24052874, 2012). "Hyperparathyroidism may be differentiated by analysis of parathyroid hormone levels, calcium, phosphorous and alkaline phosphatase." (PMID 22640403, 2012). "In the same study, only moderate to severe hyperparathyroidism (PTH concentrations ≥600 pg/mL), but not more modest increases in PTH, was associated with an increase in the relative risk of death." (PMID 22254038, 2010).
hyperparathyroidism (continued). "While the data from the reviewed studies supports the possibility that PTH affects the immune system, further research is needed, particularly since this abnormality could be reversed with the treatment of hyperparathyroidism." (PMID 20886005, 2010). "Likewise, weekly administration of an Aβ42-neutralizing antibody suppressed tonic PTH hypersecretion and synergized with daily administration of cinacalcet, a calcimimetic that activates CaSR homodimers, to reduce serum PTH levels in aging-induced hyperparathyroidism (HPT) mice." (PMID 40492090, 2025). "However, brown tumors may exhibit histological features similar to GCT; therefore, hyperparathyroidism must be excluded through a parathyroid hormone (PTH) assay." (PMID 41450931, 2025). "Finally, the authors speculated that secondary hyper-hyperparathyroidism and increased serum PTH levels played minimal roles in periodontal disease in hemodialysis patients, a speculation that we also find plausible." (PMID 40097880, 2025). "Selective venous sampling, which measures PTH gradients across various venous sites, may be used in clinical practice to localize hypersecreting tissue, particularly in patients with persistent or recurrent hyperparathyroidism after prior surgery." (PMID 40710393, 2025). "Hyperparathyroidism is a common consequence of renal failure due to the kidneys’ reduced ability to excrete phosphate and activate vitamin D. This leads to elevated parathyroid hormone (PTH) levels as the body attempts to compensate for imbalances in calcium and phosphorus metabolism." (PMID 41140700, 2025). "Moreover, in patients with long-standing hyperparathyroidism, PTH hyporesponsiveness, or a desensitization of the skeleton, may develop, reducing the diagnostic accuracy of PTH levels in the evaluation of bone turnover." (PMID 38817914, 2024). "As hypercalciuria and intestinal calcium malabsorption were not evaluated in our study, and we included patients with PTH values up to 100 pg/mL, a certain number of cases of Secondary Hyperparathyroidism, due to these causes, were probably included in our sample." (PMID 37286864, 2023). "Moreover, it was associated with hyperparathyroidism (OR: 3.48) and with PTH levels, independent of vitamin D, calcium/phosphate levels, and motor status." (PMID 36873448, 2023). "Symptomatic hyperparathyroidism, especially with bone involvement, high values of PTH and albumin-corrected serum calcium, and a US diameter of more than 3 cm, may be considered features of high suspicion of parathyroid carcinoma, differentiating it from the atypical parathyroid tumour." (PMID 37834940, 2023). "The genetic deletion of Fgf23 in Dmp1KO mice reduced PTH levels by 50%, and 1,25(OH)2D levels were reduced proportionally to PTH levels, suggesting that the increased 1,25(OH)2D levels observed in Dmp1KO mice are mainly driven by persistent hyperparathyroidism." (PMID 37943605, 2023). "If PTH alters the effect of FGF23 excess, then the magnitude of the causal effect of FGF23 on TmP/GFR could be lessened by hypoparathyroidism or it could be augmented by hyperparathyroidism." (PMID 33615106, 2021). "As we pointed in the previous study, PTH levels might be influenced by multiple pharmaceutical drugs in short term, while the size of parathyroid gland might be a much more accurate marker reflecting the long-term hyperparathyroidism status." (PMID 29907149, 2018). "To date, reports have shown that more than 10% of patients with hyperparathyroidism may have a germline mutation involving the MEN1, RET, cell division cycle 73 (CDC73), calcium-sensing receptor (CASR), cyclin-dependent kinase inhibitor (CDNK1B), or PTH genes." (PMID 29983117, 2018). "Hyperparathyroidism, which is increased parathyroid hormone (PTH) levels in the blood, could cause delayed or non-union of bone fractures." (PMID 30181648, 2018).
hyperparathyroidism (continued). "On the other hand, some clinical reports suggested that hyperparathyroidism, which is increased parathyroid hormone (PTH) levels in the blood, could cause delayed or non-union of bone fractures." (PMID 30181648, 2018). "Moreover, evaluating KS patients and controls with the same 25(OH)D levels, the mean PTH values (50.03 ± 17.95 versus 30.25 ± 12.21 pg/mL) and the percentage of hyperparathyroidism (17.5% versus 2.5%, p < 0.0001) were significantly higher in KS children and adolescents." (PMID 27413371, 2016). "This postrenal transplant hyperparathyroidism could be treated with a calcimimetic or parathyroidectomy, although posttransplant parathyroidectomy may decrease renal transplant function as PTH has a known positive regulatory effect on renal perfusion and glomerular filtration rate." (PMID 27493801, 2016). "Interestingly, the prevalence of pretransplantation hyperparathyroidism was very high (mean pretransplantation PTH: 88 pmol/L) and PTH levels were similar amongst all modes of dialysis during this period and did not correlate with duration on dialysis prior to renal transplant." (PMID 27493801, 2016). "The review also suggests that potential associations with cognition may not be limited to hyperparathyroidism but extent to generally abnormal PTH levels." (PMID 26010883, 2015). "Furthermore, increased circulating concentrations of PTH might stimulate adrenal aldosterone synthesis, initiating a vicious cycle between hyperparathyroidism and hyperaldosteronism leading to more pro-inflammatory, pro-oxidant and pro-fibrotic actions." (PMID 26308451, 2015). "Because relative hypoparathyroidism is a more frequent finding in elderly patients than in younger patients, we consider that the higher prevalence of hyperparathyroidism in younger individuals could result in relatively better PTH control in the older population." (PMID 23865464, 2013). "Finally, the findings of this study showing a significant relationship between higher PTH plasma levels and prolonged P300 latency as well as a decrease in BMD suggest that hyperparathyroidism and elevated PTH due in part to age may lead to dementia and OP." (PMID 19825157, 2009). "Systemic conditions like hyperparathyroidism, which can present with brown tumors mimicking ABC or CGCG, were ruled out by normal serum calcium (9.8 mg/dL), phosphorus, and parathyroid hormone levels." (PMID 41498017, 2026). "Parathyroid hormone (PTH) abnormalities were common, with 53.6% of patients exhibiting hyperparathyroidism (mean PTH 1210.2 ± 753.2 pg/mL), 39.3% having normal levels, and 7.1% presenting with hypoparathyroidism." (PMID 41010736, 2025). "Hyperexpression of miR-24 inhibits production of parathyroid hormone by binding CDKN1B/p27, CDKN2A/p16, TGFβ1, and CASP8 transcripts, which are involved in the development of hyperparathyroidism." (PMID 40217882, 2025). "According to the Fifth International Workshop on Evaluation and Management of Primary Hyperparathyroidism, the diagnosis of PHPT relies on laboratory test results, which primarily reveal elevated levels of PTH and calcium in the blood." (PMID 39941666, 2025). "Unlike functional parathyroid carcinomas (PC), which typically present with severe hyperparathyroidism (HPT) and are monitored via serum calcium and parathyroid hormone (PTH) levels, NFPC lacks biochemical markers and is monitored solely through imaging." (PMID 40762649, 2025). "Hyperactive tissues within the ectopic lesions secrete an excess amount of parathyroid hormone (PTH), leading to hyperparathyroidism." (PMID 40062044, 2025). "Concerning the effect of niacin on parathyroid hormone (PTH), there was hyperparathyroidism in all study populations as a result of renal failure." (PMID 41140700, 2025).
hyperparathyroidism (continued). "Elevated PTH levels after TT particularly when still under GA such as during closure or if additional procedures such as lateral neck dissections are performed following thyroidectomy may raise suspicion of hyperparathyroidism and result in unwarranted parathyroid exploration." (PMID 39831132, 2025). "Although it is unclear whether the sporadic observations of hyperparathyroidism and Ca2+ disturbances are directly linked to CNNM2 function, these findings indicate that CNNM2 variants should be considered earlier in individuals with unsolved Ca2+ and PTH phenotypes." (PMID 38519529, 2024). "Taken together, these results indicate that hyperparathyroidism is prevalent in XLH and reinforces the need for PTH monitoring." (PMID 38226986, 2024). "Patients with severe hyperparathyroidism had lower serum albumin and Cr/BSA compared with patients with PTH levels in the target range or mild hyperparathyroidism." (PMID 37484844, 2023). "Hyperparathyroidism (HPT) is a generalized disturbance of calcium (Ca) and phosphate metabolism that occurs as a result of the oversecretion of parathyroid hormone (PTH), and it can involve many of the organs and systems within the human body." (PMID 37051197, 2023). "Hyperparathyroidism (HPT) is a common endocrine disorder, characterized by aberrant parathyroid gland enlargement, excessive circulating parathyroid hormone (PTH), and disturbed bone and mineral metabolism." (PMID 37854190, 2023). "Hyperparathyroidism (HPT) is a complex disease characterized by abnormal calcium and phosphorus metabolism due to excessive parathyroid hormone (PTH) secretion." (PMID 37113486, 2023). "Patients with overt hyperparathyroidism (HPHPT group) had significantly elevated levels of calcium and parathyroid hormone (p=0.00)." (PMID 37065752, 2023). "Nevertheless, even with serum PTH level at the limit of normal, [18F]fluorocholine PET/CT localized a lesion in 55.56% of cases of hyperparathyroidism." (PMID 35983092, 2022). "Parathyroid hormone (PTH) levels above 65 ng/L, corresponding to hyperparathyroidism, were observed in 1.5% of all mothers (1.2% in light‐skinned vs. 2.9% in dark‐skinned; p = .44)." (PMID 36514767, 2022). "Hyperparathyroidism (HPT) is an endocrine disease related to the elevated metabolism of calcium (Ca), vitamin D, and phosphate (P) due to the excessive secretion of parathyroid hormone (PTH)." (PMID 36295623, 2022). "By presenting this case, we wanted to highlight the importance of monitoring PTH concentrations in patients with TIO, as there is a possibility of masked hyperparathyroidism." (PMID 35090436, 2022). "Hyperparathyroidism (HPT) is the third most common endocrine disorder and is characterized by elevated or inappropriately normal parathyroid hormone (PTH) secretion, which regulates calcium and phosphorus metabolism." (PMID 33669104, 2021). "The aim of this study was to further evaluate the possible existence of hyperparathyroidism in HAC by measurement of both circulating intact and whole PTH concentrations in affected and unaffected dogs." (PMID 32582784, 2020). "End-stage renal disease (ESRD) is often complicated by the development of hyperparathyroidism (HPT); more than 80% of patients with a glomerular filtration rate (GFR) below 20 mL/min develop serum PTH levels exceeding the upper limit of normal." (PMID 30415287, 2018). "Calcium and serum phosphorus, parathyroid hormone (PTH) and urinary calcium for characterization of hyperparathyroidism (present in MEN-1 in more than 90% of cases) should be performed at least once at diagnosis." (PMID 29324681, 2018). "Cortical porosity and marrow fibrosis have also been reported in the bone tissue of hyperparathyroidism patients and PPR*Tg mice, which constitutively express active PTH/PTHrP receptors." (PMID 28394900, 2017).
hyperparathyroidism (continued). "These cases illustrate how one can acquire spuriously high PTH levels from grafted forearms after TPT-ATx, and thus the potential to falsely diagnose recurrent hyperparathyroidism." (PMID 28645310, 2017). "Our studies provide evidence that in hyperparathyroidism, continuous up-regulation of MCP-1 expression is required for PTH-mediated catabolic effects on bone." (PMID 29127344, 2017). "HPT = hyperparathyroidism, MEN = Multiple Endocrine Neoplasia Syndrome, PTx = parathyroidectomy, PTH = parathormone, VD = Vitamin D." (PMID 27928436, 2016). "Considering this PTH threshold, about one-third of hypovitaminosis D young CHD patients showed hyperparathyroidism." (PMID 26955207, 2016). "Tertiary hyperparathyroidism in XLH has been well described and is thought to result from chronic stimulation of PTH by phosphorus supplements, leading to autonomous secretion from hyperplastic or adenomatous parathyroid glands." (PMID 24594262, 2014). "Parathyroid hormone (PTH) level is already elevated in patients with mild CKD and prevalence of hyperparathyroidism rises substantially when glomerular filtration rate (GFR) decreases." (PMID 22867424, 2012). "In cats, it has been recommended that serum phosphate and parathyroid hormone be monitored, and phosphate-restricted dietary management and intestinal phosphate binders be used to retard the progression of CKD and accompanying hyperparathyroidism." (PMID 20885927, 2010). "Elevated PTH levels during and after thyroidectomy are common and not always an indication of undiagnosed hyperparathyroidism if there was no preoperative indication of such." (PMID 39831132, 2025). "Noteworthy, the fibrosis is very likely not secondary to hyperparathyroidism given that her PTH levels were within normal limits, consistent with previous observations in patients with pycnodysostosis." (PMID 40144453, 2025). "Hyperparathyroidism (HPT) is a pathological condition characterized by hyperactivity of the parathyroid glands, resulting in aberrantly elevated levels of parathyroid hormone (PTH) in the circulatory system." (PMID 39941666, 2025). "The patient tested negative for hyperparathyroidism and pheochromocytoma, with normal values for PTH, total calcium levels, and serum methanephrines and normetanephrines." (PMID 39124658, 2024). "VDRAs can be considered for treatment of severe hyperparathyroidism (which is persistent and progressive), although an optimal PTH target for people with non-dialysis CKD has not been established." (PMID 39119524, 2024). "In hyperparathyroidism (HPT) cases, the overproduction of parathormone (PTH) may affect any part of the skeleton, potentially leading to the formation of single or multiple cyst-like lesions of bone, known as brown tumors." (PMID 39213924, 2024). "More than 70% of patients had pre-transplant hyperparathyroidism (i-PTH >80 pg/mL) with or without pre-transplant calcimimetic treatment." (PMID 38751772, 2024). "Prior to surgery, the patient tested negative for hyperparathyroidism and pheochromocytoma, with normal values for PTH, total calcium levels, and serum methanephrines and normetanephrines." (PMID 39124658, 2024). "In secondary, hyperparathyroidism due to renal leak syndrome, for instance, surgical treatment would not be able to maintain normal PTH levels over time." (PMID 39055046, 2024). "The use of calcitriol and VDRAs should be reserved for people with CKD stages 4 and 5 with severe hyperparathyroidism (ungraded), though the optimal parathyroid hormone (PTH) target is not known in people not on dialysis." (PMID 39119524, 2024). "Among the hypercalcemic patients, 73 (13.6%) were screened for hyperparathyroidism (PHPT) with an intact parathyroid hormone (PTH) test, while 464 (85.4%) were not screened." (PMID 38143641, 2023).